SPINT2 (serine peptidase inhibitor, Kunitz type 2)
Diseases named in the same sentence as SPINT2 in open-access papers (continued):
Sharing a sentence is not in itself a finding about the gene and the disease.
preeclampsia (2 papers, 2021 to 2022). Preeclampsia is a hypertensive disorder of pregnancy that is characterized by new-onset hypertension with proteinuria presenting after 20 weeks of gestation, and depending on mild or severe forms may initially present with severe headache, visual disturbances, and hyperreflexia. "Preeclampsia is associated with placental and systemic inflammation, and we therefore assessed whether SPINT2 is influenced by pro-inflammatory stimuli." (PMID 34299087, 2021). "SPINT2 was elevated in the placentas of patients who required delivery for preterm preeclampsia (p = 0.025)." (PMID 34299087, 2021). "At 36 weeks’ gestation, circulating SPINT2 was also elevated (p = 0.03) in women who were destined to develop term preeclampsia (n = 23, median = 2233 pg/mL, IQR: 1643–2661 pg/mL), relative to the controls (n = 182, median 1644 pg/mL, IQR: 1218–2480 pg/mL)." (PMID 34299087, 2021). "At 36 weeks, circulating SPINT2 was elevated in patients who later developed preeclampsia (p = 0.028; median = 2233 pg/mL vs. controls, median = 1644 pg/mL), or delivered a small-for-gestational-age infant (p = 0.002; median = 2109 pg/mL vs. controls, median = 1614 pg/mL)." (PMID 34299087, 2021). "Similarly, there was elevated circulating SPINT2 at 36 weeks in those women who were destined to develop preeclampsia, while earlier gestation levels were unchanged, relative to the controls." (PMID 34299087, 2021). "It is interesting that SPINT2 mRNA and protein are both significantly elevated in preeclamptic (without FGR) placentas, whereas the placentas plagued by concurrent preeclampsia and FGR had decreased SPINT2 mRNA, but elevated protein." (PMID 34299087, 2021). "Unlike SPINT1, circulating SPINT2 is not consistently dysregulated in diseases of placental insufficiency—in preeclampsia or foetal growth restriction." (PMID 34299087, 2021). "Given that SPINT2 has not previously been analysed in the human placenta, this study first characterised its expression in pregnancies that were known to be compromised by FGR and/or preeclampsia." (PMID 34299087, 2021). "The expression of SPINT2 mRNA in the preterm placentas was decreased in concurrent FGR and preeclampsia, but elevated where only preeclampsia is present (i.e., with AGA); whereas, SPINT2 protein expression was increased in all cases of preeclampsia (with and without FGR)." (PMID 34299087, 2021).
viral infection (2 papers, 2021 to 2023). "At present, SPINT2 is the focus of research related to cancer and viral infections; there has been no research on the association between this enzyme and insomnia." (PMID 38090272, 2023).
acute myeloid leukaemia (1 paper, 2019). "Thus, to investigate whether this loss of expression was due to SPINT2/HAI‐2 methylation, BMMSC from MDS and de novo acute myeloid leukaemia (de novo AML) patients were treated with 5‐Azacitidine (Aza), a DNA methyltransferase inhibitor." (PMID 30484958, 2019).
anal atresia (1 paper, 2018). "However, two heterozygous SPINT2 nucleotide alterations were identified in exon seven of two non-sCSD patients with anal atresia." (PMID 29499739, 2018).
asthma (1 paper, 2015). "We found that RAMP1, FSCN1, PSTG1 and SPINT2 genes could be associated with the development of severity of asthma." (PMID 26302899, 2015). "However, no studies showed an association of FSCN1 (fascin actin-bundling protein 1) and SPINT2 (serine peptidase inhibitor, Kunitz type, 2) with the evolution of asthma severity." (PMID 26302899, 2015).
colitis (1 paper, 2008). Inflammation of the colon. "Further, during the course of acetic acid-induced experimental colitis in an in vivo mouse model, Spint1 but not Spint2 was upregulated in the recovery phase, a process that requires cellular regeneration." (PMID 18506145, 2008).
COVID-19 (1 paper, 2021). A disease caused by infection with severe acute respiratory syndrome coronavirus 2. "We found SPINT2 in the permissivity signature from which we filtered out viral induced genes, suggesting that this gene could be used as a marker for predicting COVID-19 disease susceptibility prior to infection, however this needs to be further evaluated." (PMID 34181691, 2021). "Finally, it is known that SPINT2 is down-regulated among different types of tumors and we were able to corroborate this by systematically evaluating bulk- and scRNA-seq datasets which suggests a possible association to the COVID-19 comorbidity observed in cancer patients." (PMID 34181691, 2021). "We found a lower expression of SPINT2 in secretory cells from COVID-19 patients with severe symptoms." (PMID 34181691, 2021). "This led us to hypothesize that shared molecular mechanisms between some chronic diseases and COVID-19 could be explained in part by the regulation of SPINT2." (PMID 34181691, 2021). "We hypothesized that SPINT2 levels would be lower in SARS-CoV-2 target cells from COVID-19 patients with severe symptoms which we could indeed observe in secretory cells from nasopharynx samples." (PMID 34181691, 2021). "We also found lower SPINT2 gene expression in samples from COVID-19 patients with severe symptoms, hence, this gene might represent a biomarker for predicting disease severity." (PMID 34181691, 2021). "We found that SPINT2 negatively correlates with SARS-CoV-2 expression in Calu-3 and Caco-2 cell lines and was down-regulated in secretory cells from COVID-19 patients." (PMID 34181691, 2021).
diabetes (1 paper, 2021). "A marked down-regulation of SPINT2 can be observed in alpha islets pancreatic cells from diabetes patients." (PMID 34181691, 2021).
Diarrhea (1 paper, 2014). Abnormally increased frequency (usually defined as three or more) loose or watery bowel movements a day. "SPINT2, whose mutations have been linked to congenital sodium diarrhea, appears to be a potent inhibitor." (PMID 24722141, 2014). "In humans, various mutations in the SPINT2 gene have been reported and shown to be linked to a syndromic form of congenital sodium diarrhea, indicating that SPINT2 likely plays a role in intestinal ionic homeostasis." (PMID 24722141, 2014).
fallopian tube carcinoma (1 paper, 2013). A carcinoma that arises from epithelial cells of the fallopian tube. "In a DNA profiling study of primary serous ovarian and fallopian tube carcinomas, the amplified genes included SPINT2, i.e., the gene encoding Bikunin." (PMID 23344037, 2013).
insomnia (1 paper, 2023). A sleep disorder characterized by difficulty in falling asleep and/or remaining asleep. "In this study, the expression levels of C2CD2L, SPINT2, APOL3, PKNOX1, and A2M exhibited clear associations with most of the 22 immune cells tested, thus suggesting that these genes may participate in the development of insomnia by regulating multiple immune cells." (PMID 38090272, 2023).
lymph node metastases (1 paper, 2008). "In a separate study conducted with a small set of tissues (n=14), we observed that B2M maintained its high prognostic accuracy for lymph node metastases (AUC=0.79) when more classical reference control genes TBP or UBP were substituted for Spint2 (not shown)." (PMID 18506145, 2008).
osteosarcoma (1 paper, 2021). A usually aggressive malignant bone-forming mesenchymal neoplasm, predominantly affecting adolescents and young adults. "Hence, I have compared the prognostic gene set for osteosarcoma, Cox univariate and multivariate analysis showed that BACE2, ING2 ALOX5AP, HLA-DMB, HLA-DRA, and SPINT2 were not the independent prognostic factors for osteosarcoma." (PMID 33520450, 2021).
pancreatic ductal adenocarcinoma (1 paper, 2018). An infiltrating adenocarcinoma that arises from the epithelial cells of the pancreas. "Notable levels of SPINT2 mRNA were confirmed in OSCC, showing the median value a little lower than pancreatic ductal adenocarcinomas that are known to overexpress SPINT2." (PMID 29545930, 2018).
placental insufficiency (1 paper, 2021). Failure of the placenta to deliver an adequate supply of nutrients and oxygen to the fetus. "Placental insufficiency is often associated with intermittent placental hypoxia; thus, we assessed the effect of hypoxia on SPINT2 expression." (PMID 34299087, 2021). "Further, the expression of SPINT2 in placental trophoblasts was expected to be regulated by hypoxia and inflammation, which are signature contributors underlying placental insufficiency." (PMID 34299087, 2021). "Indeed, an association between circulating SPINT2 and placental insufficiency is apparent only at term (and near term, from 36 weeks onwards), with no distinction between the cases and controls in weeks 24–34, nor at preterm delivery (<34 weeks)." (PMID 34299087, 2021). "Having found SPINT2 levels to be elevated in placental insufficiency, we used in vitro methods to examine the effect of hypoxia and pro-inflammatory cytokines on the trophoblasts of the placenta, early in gestation and at term." (PMID 34299087, 2021). "This study aimed to characterise SPINT2 expression in placental insufficiency." (PMID 34299087, 2021). "While derangements in SPINT2 expression were apparent in the cases of placental insufficiency-mediated pregnancy complications, the measured fluctuations do not reliably reflect the disease status, making SPINT2 an overall poor biomarker candidate." (PMID 34299087, 2021).
tumor (46 papers, 2006 to 2025). "SPINT2, which is a putative tumor suppressor, encodes a transmembrane protein with two extracellular protease inhibitor domains (Kunitz domains) that act on a variety of serine proteases." (PMID 34962618, 2022). "This is supported by data from the PRECOG and KM-Plotter meta-analysis databases, which point to a tumor-type-specific inverse association of SPINT2 gene expression with survival." (PMID 31737572, 2019). "Serine protease inhibitor kunitz type 2 (SPINT2/HAI-2) has been implicated in tumor pathogenesis through its influence on cell cycle progression, tumor cell migration and invasion, angiogenesis, and protection from apoptotic stimuli." (PMID 28512631, 2017). "Other interesting features are that KIF18, a member of the kinesin superfamily of microtubule-associated molecular motors is overexpressed whereas SPINT2 is a putative tumor suppressor that appears to be underexpressed." (PMID 25887408, 2015). "In addition to their association with AML prognosis, CPNE8, HOXA10, and SPINT2 were also found to be prognostically relevant across multiple tumor types." (PMID 39555062, 2024). "Interestingly, SPINT2 a transmembrane protein that inhibits serine proteases implicated in cancer progression, acts as a putative tumor suppressor when hypermethylated." (PMID 31349573, 2019). "SPINT2 is a serine protease inhibitor where decreased expression facilitated STYK1-mediated tumor progression." (PMID 38260835, 2023). "We validated differentially expressed proteins at the transcriptional level in clinical tumor specimens, association with patient survival, and absolute concentration to yield three biomarker candidates: MDK, GDF15, and SPINT2." (PMID 38260835, 2023). "Considering the function of SPINT2, its role as tumor suppressor was reported in several malignancies such as breast cancer, prostate cancer, renal cell carcinoma, brain cancer and others." (PMID 36690660, 2023). "Since SPINT2 has been reported to act as a putative tumor suppressor in some cancer types, our findings suggest the mechanism of its tumor suppressing activity." (PMID 34962618, 2022). "After verifying the relation between STYK1 and its downstream target SPINT2, we further detected the SPINT2 expression by IHC tissue array analysis containing 347 paired tumor-normal samples." (PMID 31164631, 2019). "The high SPINT2 expression was negatively correlated to tumor invasion, distant metastasis, differentiation, and AJCC 8th stage." (PMID 31164631, 2019). "We verified that elevated serine threonine tyrosine kinase 1 (STYK1) or decreased serine peptidase inhibitor Kunitz type 2 (SPINT2/HAI-2) expression significantly correlated with poor prognosis, tumor invasion, and metastasis of NSCLC patients." (PMID 31164631, 2019). "Decreased SPINT2 expression was positively correlated to tumor invasion, distant metastasis, differentiation, and AJCC 8th stage." (PMID 31164631, 2019). "Then, we analyzed the effect of SPINT2 deletion on tumor formation in nude mice using the SAS sublines." (PMID 29545930, 2018). "Two of these, GSTP1 and SPINT2 were previously reported tumor suppressor genes which were hypermethylated in tumors with corresponding down-regulated gene expression, while the other 2 (CYB5R2 and SH3YL1) represent potential novel tumor suppressor genes." (PMID 25093504, 2014). "Although we are unaware of any published evidence implicating DUSP6 or SPINT2 as tumor suppressors in B lymphoid malignancies, their expression was found to be increased in our experiments where IL-4 impaired EBV-induced transformation." (PMID 23724103, 2013). "We have expanded our previous analysis of HAI-2/SPINT2 promoter methylation in RCC (38%) to incorporate all tumours analysed for KTN19 and CXCL16 promoter methylation." (PMID 18195710, 2008). "Conversely, in cancer therapy, inducing SPINT2-mediated c-Met suppression could promote tumor cell senescence, limiting proliferation." (PMID 40838961, 2025).
tumor (continued). "Additionally, epigenome screening identified serine protease inhibitor kunitz-type 2 (SPINT2–an inhibitor of HGF activation) as a potential tumor suppressor gene in MB." (PMID 36034555, 2022). "We also found SPINT2 down-regulation in tumor types which could have implications for the observed comorbidities in COVID-19 patients with cancer." (PMID 34181691, 2021). "Using published datasets, we show that in these comorbid diseases, SPINT2 is downregulated, which might lead to an increase of the infectivity of cells in disease-tissues such as endocrine cells of diabetic patients or cells from tumor tissues." (PMID 34181691, 2021). "Currently, it remains unknown how SPINT2 may promote tumor progression." (PMID 31737572, 2019). "Then we investigated whether SPINT2 involves in STYK1-mediated tumor progression." (PMID 31164631, 2019). "We also found the high expression of tumor suppressor gene SPINT2 at early stage and subsequent up-regulation of the oncogene JUNB, revealing an increase of metastasis potential over the tumor evolution of metabolism-type PCCs." (PMID 38407266, 2024). "Among these genes, SPINT2, LNX1, FOXA2, and SOSTDC1 were reported to be related to tumor progression, whereas TYROBP, TREM2, IL23R, CSF2RB, TRAF1, and TGFBR1 were closely associated with immune response." (PMID 36611170, 2023). "The increased levels of SPINT2 in HGSC plasma and its high expression in tumor cells suggest a tumor-promoting function, which contrasts results published for other entities." (PMID 31737572, 2019). "The protein product of SPINT2 inhibits HGF activator, which prevents the formation of active hepatocyte growth factor, has been taken as a putative tumor suppressor." (PMID 28086821, 2017). "Furthermore, the spatial pattern between XBP1 and SPINT2 aligns with previous findings, which identify SPINT2 as a hub gene for tumor and intermediate regions, while XBP1 is a hub gene in the tumor region only." (PMID 39954675, 2025). "Moreover, NSCLC patients with deep tumor invasion (T3/T4) and high AJCC 8th stage (stages III/IV) had significantly lower expression of SPINT2 than these with superficial tumor invasion (T1/T2) and low AJCC 8th stage (stages I/II)." (PMID 31164631, 2019). "The Spint2 transcript was homogenously expressed in the tumor epithelium, but not in the stroma, as identified by the mCAF-specific transcript Mfap5." (PMID 30514914, 2018). "In addition to SPINT2, four further genes (CDH1, PLAU, IGFB3 and MT1G) had previously been reported to undergo promoter region hypermethylation in RCC tumours." (PMID 18195710, 2008). "Thus, because Spint1 and Spint2 serve to inhibit the activity of HGF, these genes have been characterised as tumour suppressors." (PMID 18506145, 2008). "OC appears to fall into the category of tumor entities where SPINT2 may have a tumor-promoting rather than suppressive role, which is suggested by two observations." (PMID 31737572, 2019). "Despite being related to the pathogenesis of several neoplasms, the role of SPINT2/HAI‐2 has not yet been fully elucidated in haematological malignances, such as MDS and de novo AML." (PMID 30484958, 2019).